YBX1 (Y-box binding protein 1)
Diseases named in the same sentence as YBX1 in open-access papers (continued):
Sharing a sentence is not in itself a finding about the gene and the disease.
glioma (36 papers, 2013 to 2025). A benign or malignant brain and spinal cord tumor that arises from glial cells (astrocytes, oligodendrocytes, ependymal cells). "Kindlin-2 and GOLPH3 (Golgi phosphoprotein 3) proteins are associated with glioma, and it appears that YBX1 protein is involved in the increased expression of EGFR and the activation of mTOR in this context." (PMID 38255791, 2024). "Our findings have uncovered a series of factors (ANXA2/NSUN2/YBX1) that can determine the alternative generation of different isoforms of B7‐H3 in glioma." (PMID 39048916, 2024). "Taken together, our study provided an explainable theory that ANXA2/NSUN2/YBX1 axis modulated the generation of B7‐H3 isoform in glioma cells." (PMID 39048916, 2024). "This highlights YBX1’s crucial role as PLK1 inhibition triggers cell death and DNA damage via YBX1 phosphorylation, offering insight into potential glioma treatment mechanisms." (PMID 38255791, 2024). "When GOLPH3 was down-regulated, it resulted in a substantial reduction in the levels of YBX1 and mTOR activity, which are both crucial for glioma cell migration and invasion." (PMID 38255791, 2024). "This phosphorylation is crucial for the nuclear translocation of YBX1 and its involvement in apoptosis surveillance in glioma stem cells." (PMID 38255791, 2024). "YBX1 exerts pro-cancer effects on glioma progression in multiple ways, regulating the expression and phosphorylation of major proteins associated with the cell cycle, adhesion, and apoptosis." (PMID 37964279, 2023). "Another study reveals that genetic or chemical inhibition of MDM2 obviously blocked Y-box-binding protein-1-mediated temozolomide resistance in glioma cells." (PMID 37291112, 2023). "For example, miR-382-5p has been shown to inhibit the proliferation, migration, invasion, and EMT of glioma cells by targeting YBX1." (PMID 37964279, 2023). "The Kaplan-Meier analysis indicated that patients with gliomas that highly expressed YBX1 (upper 50th percentile) had a shorter OS." (PMID 36805592, 2023). "YBX1 mRNA was higher in glioma tissues than in normal tissues and expressed in the highest concentrations in the WHO grade IV glioma GBM." (PMID 36805592, 2023). "Further, several studies reported that the increased levels of YBX1 protein is connected to tumor progression as well as poor prognosis in glioma and other cancers." (PMID 31358880, 2019). "In terms of common molecular signatures, both NSCs and glioma CSCs exhibit Y-box binding protein 1 (YB-1), Sox-2, Nestin and Msi1 expression which are lost upon differentiation." (PMID 30510501, 2018). "Golgi phosphoprotein 3 (GOLPH3) is also found to be upregulated in gliomas and involved in glioma cell migration and invasion via the mammalian target of rapamycin (mTOR)-Y-box binding protein-1 (YB1) pathway." (PMID 26098895, 2015). "Coincidentally, YBX124, 25 as a 5mC “reader” displayed a deficient interaction with B7‐H3 transcripts in U87MG, and the expression of YBX1 was weak in U87MG compared to other four glioma cells, but was strong in glioma specimens with abundant expression of 2Ig." (PMID 39048916, 2024). "Interestingly, YBX1, a transcription factor involved in DNA repair, highly expressed in cancers, and known to promote cell growth and to inhibit differentiation in glial tumors is highly central in both CNS subtype networks (LGG and GBM)." (PMID 37200395, 2023). "Interestingly, YBX1 levels were also higher in the microsomal fractions of lower grade gliomas (6.8 fold change in Grade II and 3.8 fold change in Grade III) with 4 and 3 unique peptides and 10, 8 PSMs, respectively." (PMID 31358880, 2019). "In glioma cells the molecular mechanism underlying GOLPH3 function in migration and invasion requires mTOR and one of its effectors, the transcription/translation regulatory protein Y-box binding protein-1 (YB1)." (PMID 25691054, 2015).
glioma (continued). "The axis of NSUN2/YBX1 can promote the generation of 2Ig of B7‐H3 in glioma, and we speculate that the abundant 2Ig takes up too much of the cell surface, causing the T cells to fail to recognize enough 4Ig, allowing the glioma to become immune escape capability." (PMID 39048916, 2024). "Single-gene knock-out and overexpression studies of CHEK2, YBX1, and YBX3 in multiple glioma cell lines revealed that these proteins positively regulate each other’s expression." (PMID 40161682, 2025). "In glioma stem cells, PLK1 interacts with YBX1 and phosphorylates serine residues YBX1–176 and 174, leading to reduced YBX1 levels and inhibition of its nuclear translocation, inducing apoptosis and DNA damage in glioma stem cells." (PMID 40799245, 2025). "By comparing among five glioma cells, we have finally found three proteins ANXA2/NSUN2/YBX1 that can explain the phenotypes in different cells." (PMID 39048916, 2024). "In glioma stem cells (GSCs), inhibiting PLK1 induces apoptosis and DNA damage by phosphorylating YBX1 at serine 174 and serine 176, impairing its nuclear translocation." (PMID 38255791, 2024). "In terms of glioma subtypes, consistent with PLK1, YBX1 is highly expressed in classic and proneural subtypes." (PMID 36805592, 2023). "We searched the expression level of candidate genes by GEPIA and found that only five genes (F11R, YBX1, BCAT1, IMPAD1, and RP2) were significantly upregulated in gliomas." (PMID 35402226, 2022). "For instance, in gliomas, miR-382-5p expression is down-modulated and miR-382-5p restrains cancer cell multiplication, migration, invasion, and EMT by targeting the oncogene YBX1." (PMID 33685351, 2021). "Our results further suggested glioma relevant targets that are involved in AKT-mTOR signaling (MAPKAPK2 and YBX1)." (PMID 23358700, 2013). "We believe that the illustration of ANXA2/NSUN2/YBX1 regulatory axis is a prerequisite to address the complicated pattern of B7‐H3 in glioma, which again highlights the problem of immunotherapy not being universally effective in the cancer population." (PMID 39048916, 2024). "Conversely, overexpression of miR-382-5P also inhibits the expression of the glioma cell epithelial markers Snail and Slug, as well as possibly negatively regulates the Y box binding protein 1 (YBX1) gene, thereby suppressing glioma migration, invasion, and the EMT process." (PMID 36479040, 2022). "As discussed under the ‘Results’ section, YBX1 is overexpressed in GBM and other grades of gliomas." (PMID 31358880, 2019). "Finally, we determined that Kindlin-2 formed a transcriptional complex with Y-box binding protein-1 (YB-1) and β-catenin that enhanced EGFR transcription and promoted glioma cell proliferation, migration, and invasion." (PMID 27713156, 2016). "Although it is not clear how exactly the expression of YBX1 itself is regulated, it is interesting to note the observation that miR-137 and miR-29b reported to regulate the expression of YBX146,47, are found to be significantly downregulated in glioma." (PMID 31358880, 2019).
sarcoma (33 papers, 2016 to 2025). A usually aggressive malignant neoplasm of the soft tissue or bone. "Pediatric sarcomas express high levels of the multifunctional Y-box binding protein 1 (YB-1), which is associated with drug resistance and metastatic properties." (PMID 38318175, 2024). "However, the increased expression of YBX1 was associated with better overall survival in adrenocortical carcinoma, liver hepatocellular carcinoma, mesothelioma, and sarcoma patients (p < 0.05)." (PMID 35861369, 2023). "The specific enhancer‐driven regulons of malignant cell clusters, such as Ybx1 in T‐cell lymphoma and AP‐1 family genes in sarcoma, were also demonstrated." (PMID 40887856, 2025). "A previous study confirmed that class I HDAC inhibitors enhance the acetylation of Y-box binding protein 1 (YB-1) and increase oxidative stress, thereby blocking sarcoma metastasis." (PMID 40260239, 2025). "A significant relationship between YBX1 expression and survival was detected in 6 cancer types: breast, liver, lung, renal papilloma, uterine cancer, and sarcoma." (PMID 38538658, 2024). "We next focused on the 4 cancer sites that affect both males and females, where YBX1 expression was identified to significantly affect survival: liver, lung, renal papilloma, and sarcoma." (PMID 38538658, 2024). "YBX1 was previously identified as a critical regulator of HIF1A expression in sarcoma leading to enhanced metastatic capacity in vivo." (PMID 36936386, 2023). "YBX1 has previously been shown to promote the invasion and metastasis of several sarcoma types, including FN and FP RMS, by binding to the 5′ untranslated region of HIFα mRNA and activating its translation." (PMID 37345125, 2023). "YBX1 protein was shown to be a critical regulator of HIF1α expression in sarcoma cells; however, less is known about the role of this protein in MSCs." (PMID 35163348, 2022). "Recently, YBX1 activates HIF-1α at the translation level by binding to the IRES sequences of the HIF-1α mRNA 5’UTR region to promote sarcoma metastasis." (PMID 31291975, 2019). "Additionally, translational regulation of hypoxia-inducing factor 1α (HIF1α) by YBX1 promoted sarcoma metastasis." (PMID 34440660, 2021). "YBX1 was reported could interact with HIF-1α 5’UTR to promote HIF-1α translation in sarcoma, we speculated that YBX1 may play as a cofactor of PTBP3 in regulating HIF-1α translation." (PMID 31291975, 2019). "Previous studies reported that YBX1 affected mRNA translation of HIF1α and MYC to promote sarcoma metastasis and leukemia progression at a posttranscriptional level." (PMID 37161388, 2023). "YBX1 and Ras-GTPase activating protein SH3 domain binding proteins 1 (G3BP1) were reported to exhibit highly correlated expression levels in sarcomas." (PMID 31481087, 2019). "In human sarcoma, the Y-box binding protein 1 (YB1) enhances the formation of SGs by binding directly to G3BP1’s 5’UTR and promoting G3BP1 mRNA translation, thus enhancing the invasion and metastasis of human sarcoma cell." (PMID 37179344, 2023). "For example, the Y-box binding protein 1 (YB-1) interacts with the 5'-untranslated region (UTR) of G3BP1, leading to the increased expression of G3BP1 and SGs, which is elevated in human sarcomas." (PMID 38110976, 2023). "For example, MS-275 promotes YBX1 acetylation at K81, enhancing its binding to the 3′UTR region of Nuclear Factor Erythroid 2-Related Factor 2 (NRF2) mRNA, which increases NRF2 translation and decreases ROS in sarcoma cells, ultimately inhibiting sarcoma metastasis." (PMID 39727969, 2024).
pancreatic cancer (32 papers, 2015 to 2026). "Despite the genomic instability and mutation-related role of YBX1, its role in pancreatic cancer seems to be insufficient." (PMID 38255791, 2024). "In pancreatic cancer, YBX1 interacts with the epigenetic regulator CBX3 to promote cancer progression by inhibiting the expression of SMAD specific E3 ubiquitin protein ligase 2 (SMURF2) and activating TGF-β signaling." (PMID 40799245, 2025). "In pancreatic cancer, mTOR affects cell proliferation and metastatic ability by regulating the phosphorylation of YBX1, further promoting the occurrence of EMT." (PMID 40573188, 2025). "In conclusion, molecules such as RUNX2, CBX3, and MYC interact with YBX1 to promote tumor progression in various malignant tumors, including bone cancer, pancreatic cancer, and rhabdomyosarcoma, among others." (PMID 40799245, 2025). "In pancreatic cancer, YBX1 binds to the GSK3B promoter and promotes the growth of pancreatic ductal adenocarcinoma through the GSK3B/Cyclin D1/Cyclin E1 pathway." (PMID 40799245, 2025). "Only several papers so far have reported the impact of YBX1 on pancreatic cancer progression and metastasis, despite its ubiquitous investigation in other cancers." (PMID 38255791, 2024). "With the aid of mass spectrometry, we found that YBX1 was O-GlcNAcylated in pancreatic cancer cells." (PMID 38575607, 2024). "Recent research shows that RRM2 promotes liver metastasis in pancreatic cancer by stabilizing YBX1 and activating the TGF-β pathway." (PMID 39766842, 2024). "Exposure to cigarette smoke extract was observed to cause an increase in the overexpression of YBX1, which subsequently led to the upregulation of CBX3 (Chromobox 3) in pancreatic cancer cells." (PMID 38255791, 2024). "This review also summarized the up-to-date advanced research on the involvement of YBX1 in pancreatic cancer." (PMID 38255791, 2024). "Consistently, YBX1 was obviously upregulated by CSE exposure in pancreatic cancer cells, suggesting a potential role of YBX1 in smoking-induced CBX3 expression in pancreatic cancer." (PMID 35637952, 2022). "Accordingly, hypoxia induced the association of YBX1 with zinc-finger E-box-binding homeobox 1 (ZEB1), a key regulator of the EMT, to promote metastasis of pancreatic cancer." (PMID 34440660, 2021). "Another miRNA known to target YBX1 is miR-216a, which suppresses YB-1-mediated metastasis in pancreatic cancer." (PMID 31632972, 2019). "YBX1 expression drives pancreatic cancer metastasis and is counteracted by microRNA(miR)-216a." (PMID 38255791, 2024). "It has been difficult to find reports on the role of YBX1 in PD-L1 expression in pancreatic cancer." (PMID 38255791, 2024). "While the role of YBX1 in bone metastasis has been extensively studied in various types of carcinomas, there is a notable lack of specific reports detailing its direct involvement in the metastasis of pancreatic cancer to the bone." (PMID 38255791, 2024). "The growing interest in YBX1 in pancreatic cancer will also be discussed." (PMID 38255791, 2024). "Similarly, LncRNA HIF1A-AS1 recruits p-YBX1 to HIF1α mRNA and consequently promotes the translation of HIF1α in pancreatic cancer." (PMID 37253771, 2023). "In summary, the YBX1/CBX3/SMURF2 signaling axis may be a promising therapeutic target in patients with smoking-related pancreatic cancer." (PMID 35637952, 2022). "Moreover, further MTS assay and Transwell assay indicated that YBX1 promoted pancreatic cancer cell proliferation and invasion by upregulating CBX3." (PMID 35637952, 2022). "Moreover, CSE-induced YBX1 overexpression contributed to the upregulation of CBX3 in pancreatic cancer cells." (PMID 35637952, 2022). "It was demonstrated that CSCs isolated from gemcitabine-resistant pancreatic cancer release vesicles that can stimulate the expression of drug-resistance-related proteins, such as P-gp, Y-box binding protein 1, and breast cancer resistance protein, in a drug-sensitive pancreatic cancer cell line." (PMID 35629286, 2022).
pancreatic cancer (continued). "Therefore, the YBX1/CBX3/SMURF2 signaling axis may be considered as a promising target for the treatment of smoking-related pancreatic cancer." (PMID 35637952, 2022). "LncRNA BX111 recruits YBX1 to activate ZEB1 expression and induce EMT, promoting metastasis and progression of pancreatic cancer." (PMID 41507135, 2026). "Mechanistically, NSUN2-mediated m5C modification suppresses TIAM2 expression through YBX1, and disruption of the NSUN2/TIAM2 axis impairs the EMT, thereby slowing pancreatic cancer progression." (PMID 40114967, 2025). "Studies have revealed abnormal expression patterns of m5C methyltransferases, including NSUN2 and NSUN6, as well as m5C-binding proteins like YBX1 and ALYREF, in cancers such as esophageal, gastric, hepatocellular, colorectal, and pancreatic cancers." (PMID 40114967, 2025). "Collectively, these results demonstrate that YBX1 upregulates CBX3, which consequently represses SMURF2 and activates the TGF-β signaling pathway and promotes malignant progression in pancreatic cancer." (PMID 35637952, 2022). "To investigate whether this interaction occurs in other pancreatic cancer cell lines, we performed immunoprecipitation assays on Capan-1 and PANC-1 cells using an anti-YBX1 antibody." (PMID 40083936, 2025). "Although neural plasticity has been reported to be important in pancreatic cancer, there are still no reports on the role of YBX1 in this process." (PMID 38255791, 2024). "Notably, one study reported that YBX1 binds to the promoter of GSK‐3β and induces GSK‐3β expression to promote the growth of pancreatic cancer cells." (PMID 38018586, 2023). "We found that Y-box binding protein 1 (YBX1), as a smoking-related protein 17 and oncogenic driver 18, could enhance the transcription of CBX3 in pancreatic cancer cells." (PMID 35637952, 2022). "Moreover, bioinformatic analyses indicated a positive correlation between YBX1 and CBX3 in the mRNA level in various cancers, including pancreatic cancer." (PMID 35637952, 2022). "Moreover, cigarette smoke extract (CSE) exposure promoted the overexpression of Y-box-binding protein 1 (YBX1), which consequently led to upregulated CBX3 in pancreatic cancer cells." (PMID 35637952, 2022). "However, there does not appear to be any research findings related to YBX1 and angiogenesis in pancreatic cancer as of yet." (PMID 38255791, 2024). "In another study, YBX1 is recruited to promote HIF1α translation by HIF1A-AS1 and lncRNA, thus mediating key glycolytic proteins, including Glucose transporter 1, hexokinase 2, pyruvate kinase muscle isozyme M2, and lactate dehydrogenase A, in pancreatic cancer." (PMID 38255791, 2024).